CD4 (CD4 molecule)
Diseases named in the same sentence as CD4 in open-access papers (continued):
Sharing a sentence is not in itself a finding about the gene and the disease.
multiple sclerosis (continued). "IFN-β, a first-line disease-modifying therapy for multiple sclerosis, reduces migration of DCs to the draining LNs and reduced their capacity to activate CD4+ effector T-cells." (PMID 32499518, 2020). "Autoreactive CD4+ T cells, which target antigens in central nervous system (CNS) myelin, are widely believed to play a critical role in the pathogenesis of multiple sclerosis (MS) in concert with other immune effectors." (PMID 30669462, 2019). "Elevated CD4/CD8 ratios have been described in stroke, Guillain-Barré syndrome and multiple sclerosis (MS) and low CD4/CD8 ratios in HIV." (PMID 31244848, 2019). "It has been recently shown that memory B cells drive proliferation of self-reactive brain-homing CD4+ T-cells in patients with multiple sclerosis and that RTX strongly reduces autoproliferation and proinflammatory cytokine responses." (PMID 30377816, 2019). "Toll-like receptor 4 (TLR4) is well known for activating the innate immune system; however, it is also highly expressed in adaptive immune cells, such as CD4+ T-helper 17 (Th17) cells, which play a key role in multiple sclerosis (MS) pathology." (PMID 31561751, 2019). "We have recently reported that CD28 autonomous signaling induces the expression of IL-17A in peripheral CD4+ T lymphocytes from healthy donors, multiple sclerosis, and type 1 diabetes patients." (PMID 31068940, 2019). "CD4+ Th17 cells are increased in patients with lupus, multiple sclerosis, and severe phenotypes of asthma." (PMID 31849948, 2019). "In multiple sclerosis models, estrogen has been shown to inhibit CD4+ T cell expansion and increase T cell apoptosis." (PMID 31701034, 2019). "ILC3 and ILC1 have remarkable similarity to CD4+ helper T cell lineage members Th17 and Th1, respectively, which are important in the pathology of multiple sclerosis (MS)." (PMID 30828332, 2019). "Experimental autoimmune encephalomyelitis (EAE) is a well-characterized mouse model of the neuro-inflammatory demyelinating disease, multiple sclerosis (MS) and is mediated by pro-inflammatory Th1 and Th17 CD4+ T-cells." (PMID 31061496, 2019). "Next-generation sequencing of CD4+ T cells isolated from a specific subtype of multiple sclerosis plaque has uncovered an unexpectedly Th2 profile of these cells." (PMID 31205957, 2019). "EAE, which mimic the human multiple sclerosis, is established as a CD4+ T cell-mediated disease model in the rodent." (PMID 30934882, 2019). "Multiple sclerosis (MS) disease activity is associated with blood‐brain barrier (BBB) disruption, which is mediated by inflammatory cytokines released by CD4+ lymphocytes." (PMID 29027376, 2018). "While it was shown in patients with multiple sclerosis that fingolimod decreases the amount of circulating CD4+ T cells, the remaining CD4+ T cells were enriched with regulatory FoxP3+ cells." (PMID 29618748, 2018). "Multiple sclerosis is a severe disease characterized by autoimmune inflammation and myelin lesions in the CNS, thought to be mediated by CD4+ T cell activation." (PMID 30050402, 2018). "Expression of NKG2C was reported on a rare CD4+ T-cell population in pathological situations, such as multiple sclerosis or cytomegalovirus (CMV) infection." (PMID 29915583, 2018). "Although EZH2 expression in brain lesions from multiple sclerosis patients seemed restricted to CD4+ and CD8+ T cells, additional sources of EZH2 expression within the CNS cannot be totally ruled out, as evidenced by EZH2 immunohistochemistry." (PMID 30367633, 2018). "In this line, we finally investigated EZH2 expression in chronic active lesions from 10 multiple sclerosis patients and observed that 8.5% (mean percentage) and 10.9% of the total CD4+ and CD8+ T cells were expressing EZH2 respectively." (PMID 30367633, 2018). "Its expression in peripheral blood CD4+ cells is elevated in stable multiple sclerosis patients as compared to healthy subjects or patients with relapses." (PMID 30280101, 2018).
multiple sclerosis (continued). "A previous study has shown that Foxa1 is expressed in some T-cells and that Foxa1+CD4+ T-cells represent a distinct subset of Treg which play an immunosuppressive role in the central nervous system in a mouse model of multiple sclerosis." (PMID 30061015, 2018). "RGC32 is also expressed in CD3+ and CD68+ cells in brains of multiple sclerosis patients as well as in peripheral blood CD4+ cells." (PMID 30280101, 2018). "In conclusion, our study show CD4+T cells specific B7-H1 is a slective inhibitor in proliferation of naïve T cells, Th17 differentiation and pathogenesis of multiple sclerosis." (PMID 29163808, 2017). "In NMO and multiple sclerosis (MS) patients and their animal models, subtypes of CD4+ T cells were elevated compared to those of HS, and we found that one corollary of these events is the lack of balance between apoptosis and anti-apoptosis in CD4+ T cells." (PMID 28174515, 2017). "A differential methylation signal with a peak at HLA-DRB1 was observed in CD4+ T cells of multiple sclerosis patients compared with controls in another study, suggesting a potential explanation for this observation." (PMID 28270189, 2017). "Three of the up-regulated miRNA species (miR-106, miR-590-5p and miR-17) in the current study are also reported to be overexpressed in CD4+ T cells in multiple sclerosis (MS) patients." (PMID 28292330, 2017). "Multiple sclerosis (MS), a self-reactive CD4 T cell-mediated demyelinated autoimmune inflammatory CNS disorder, is classified as a prototypic heterogeneous autoimmune condition, mainly mediated by autoreactive Th1 cells and pathogenic Th17 cells." (PMID 27738345, 2017). "Considerable attention has been given in recent years to the role of CD4+ T helper (Th) 17 cells in the pathogenesis of multiple sclerosis." (PMID 28336414, 2017). "T cell-mediated responses involve both CD4+ and CD8+ T cells, and the pathogenic roles of CD8+ T cells in neuroinflammatory diseases such as multiple sclerosis and neurodegenerative diseases are being increasingly recognized." (PMID 28651603, 2017). "Considerable attention has been given to CCR6+ IL-17-secreting CD4+ T cells (Th17) in the pathology of a number of autoimmune diseases including multiple sclerosis (MS)." (PMID 28336414, 2017). "Specific miRNAs are involved in the pathogenesis of multiple sclerosis (MS), during which IL-17-producing CD4+ T helper (Th17) cells accumulate in the central nervous system (CNS)." (PMID 28400721, 2017). "T-cell expression of Hrd1 is higher in patients with multiple sclerosis than in healthy individuals, and knockdown of Hrd1 in human CD4+ T cells inhibits activation and differentiation to Th1 and Th17 cells." (PMID 27417417, 2016). "As discussed in multiple sclerosis, overexpression of β-arrestin 1 in CD4+ T, as well as other T lymphocytes has also been documented in PBC." (PMID 27669210, 2016). "CD4+ T cell-mediated autoimmune responses are crucial in the pathogenesis of multiple sclerosis and, to some extent, AD." (PMID 26772975, 2016). "The bradykinin B1R mRNA is upregulated in blood CD4+ lymphocytes from patients diagnosed with active multiple sclerosis." (PMID 26844555, 2016). "FTY720 treatment increases TCF-1 expression in CD4+ T cells from multiple sclerosis patients as well as from healthy individuals." (PMID 26714756, 2015). "Multiple sclerosis (MS) is genetically a T helper cell (CD4+ T cell)-mediated autoimmune disease that is characterized by chronic inflammation in the central nervous system (CNS) and relapse in over two thirds of patients." (PMID 26193120, 2015). "EAE is regarded as a mouse-model of human multiple sclerosis, in which auto-reactive CD4 T-cell-mediated demyelization is triggered in the CNS." (PMID 25759692, 2015). "In patients with AIH, as in those with multiple sclerosis or lupus, low numbers of functional CD4+ Tregs have been reported." (PMID 26106627, 2015).
multiple sclerosis (continued). "Strikingly, similar Eomes+ CD4+ T cells are increased in the peripheral blood and cerebrospinal fluid from patients in a progressive state of multiple sclerosis." (PMID 26436530, 2015). "CD39+ Tregs show preferential suppression over CD4+ Th17 immunity and defective numbers of these cells have also been described in patients with multiple sclerosis." (PMID 26106627, 2015). "Autoreactive CD4+ T-cells are considered to play a major role in the pathogenesis of multiple sclerosis." (PMID 25738751, 2015). "To determine the relevance of TCF-1 in multiple sclerosis pathogenesis, we first assessed its expression in CD4+ T cells from multiple sclerosis patients." (PMID 26714756, 2015). "Differential expression of the miR-17-92 cluster had previously been reported in relation to cancers and in multiple sclerosis, and it is involved in the modulation of the proliferation and activation of naive CD4+ T cells." (PMID 25487315, 2015). "We characterized the frequency of total and naïve CD4+ T cells in multiple sclerosis patients before and 3 months after FTY720 treatment." (PMID 26714756, 2015). "Blockade of TNFSF10 expressed in CD4+ myelin-specific T cells reduces caspase-dependent neuronal cell death in an experimental animal model for multiple sclerosis." (PMID 24932510, 2014). "Active vitamin D (1,25(OH)2D) more potently induces CD4+CD25+Foxp3+ (regulatory) T cells from PBMCs of female than male subjects with multiple sclerosis." (PMID 23826346, 2013). "Increased expression of miR-27b, miR-128, and miR-340 in CD4+ T cells has been reported in multiple sclerosis." (PMID 23386861, 2013). "Migration of encephalitogenic CD4+ T lymphocytes across the blood-brain barrier is an essential step in the pathogenesis of multiple sclerosis (MS)." (PMID 24282598, 2013). "It is known that EAE is mainly CD4+ Th1 and/or Th17 pathogenic T cells driven, but CD8+ T cells are much more dominant in multiple sclerosis." (PMID 23577171, 2013). "Th1-like IFN-γ producing CD4+CD25+FoxP3+ Treg are present in the blood of multiple sclerosis and renal transplant patients during active immune responses." (PMID 23935597, 2013). "Multiple sclerosis (MS) is thought to be a CD4+ T cell mediated autoimmune demyelinating disease of the central nervous system (CNS) that is rarely diagnosed during infancy." (PMID 23705890, 2013). "CD4+CD45RO+ memory T-cells from multiple sclerosis (MS) patients showed a reduced ability to suppress NLRP3 inflammasome activation, however their suppressive ability was recovered following in vivo treatment with IFNβ." (PMID 22768094, 2012). "Multiple sclerosis (MS) is an autoimmune disease of the central nervous system, and CD4+ T cells form the core immunopathogenic cascade leading to chronic inflammation." (PMID 22203863, 2012). "For instance, in multiple sclerosis, Treg cells isolated by CD4+CD25high expression had impaired function, but Treg cells defined as CD4+CD25highCD127low/− had the same suppressive function compared to controls." (PMID 21494636, 2011). "Impaired suppressive capacity of CD4+CD25+FOXP3+ regulatory T cells (Treg) from peripheral blood of patients with multiple sclerosis (MS) has been reported by multiple laboratories." (PMID 21437244, 2011). "Albeit several studies pointed out the pivotal role that CD4+T cells have in Multiple Sclerosis, the CD8+ T cells involvement in the pathology is still in its early phases of investigation." (PMID 20174631, 2010). "Estrogen was shown to directly influence cytokine secretion by CD4 T-cell clones isolated from multiple sclerosis patients." (PMID 23675060, 2008). "Sexual hormones especially testosterone promotes IFN-γ production from CD4 cells isolated from multiple sclerosis patients and estradiol promotes IL-4 cytokines in spleen cells of C57BL/6 mice." (PMID 23675060, 2008). "Moreover, MCUaKD in rat CD4+ T-cells suppresses autoimmune responses in an experimental autoimmune encephalomyelitis (EAE) multiple sclerosis model." (PMID 39623165, 2025).
multiple sclerosis (continued). "Importantly, in CD4+ T cells of multiple sclerosis patients, both Egr-1 and Foxp3 were found to decrease." (PMID 40235598, 2025). "However, on the basis of previous studies in humans, the expression of PD−1 on pathogenic CD4+ T cells in chronic ulcerative colitis (UC) and inflammatory bowel disease (IBD) differs from that in other inflammatory diseases, including multiple sclerosis." (PMID 40702356, 2025). "In experimental autoimmune encephalomyelitis and a murine model of multiple sclerosis (MS), the inhibition of Ang II signaling reduced the autoreactive T-cell populations while increasing the CD4+ FoxP3+ regulatory T-cells, potentially reversing the disease progression." (PMID 40722848, 2025). "This receptor is also involved in the Sema4B-mediated inflammation in microglia/macrophages, the Sema4D-mediated cartilage destruction, the Sema4A-induced secretion of IL-17 by CD4+ T cells of systemic sclerosis patients and the Sema4D-mediated inflammation in a mouse model of multiple sclerosis." (PMID 40598553, 2025). "Similarly, studies of peripheral blood lymphocyte subsets in multiple sclerosis patients revealed that the proportion of HLA-DR+ CD4+ T cells was significantly lower than the controls." (PMID 38941430, 2024). "Many diseases that have an “immune component” may skew the CD4/CD8 ratio such as multiple sclerosis and emphysema." (PMID 39728019, 2024). "CD4+ memory T cells developed by antigen exposure or the cytokine milieu communicate with various immune and non‐immune cellular networks within distinct microenvironments in human chronic autoimmune diseases such as multiple sclerosis." (PMID 39300613, 2024). "Other identified pathways included the pulmonary fibrosis idiopathic signaling pathway in CD4+ T-cells (p = 9.33E − 06), the multiple sclerosis signaling pathway and the IL-15 production pathway in CD8+ T-cells (p = 9.55E − 07 and p = 3.63E − 05, respectively)." (PMID 39407252, 2024). "Also, proteins encoded by human orthologs of PLP1, MBP, and MOBP are known to be antigens recognized by CD4+ T cells in multiple sclerosis patients." (PMID 36817487, 2023). "CD4+ T cells play a central role in the pathogenesis of multiple sclerosis." (PMID 37765078, 2023). "In our work, we evaluated the profile of cytokines and chemokines, as well as the production of double positive CD4+ T cells for the production of IFNγ IL-17 in patients with multiple sclerosis, at different stages of the disease and undergoing different treatments." (PMID 36140164, 2022). "CD4+ and CD8+ T lymphocytes have been pathologically implicated in patients with demyelination conditions, such as experimental autoimmune encephalomyelitis and multiple sclerosis." (PMID 36113749, 2022). "Moreover, this increased expression has been described in monocytes from Sjögren syndrome and CD4 T cells from multiple sclerosis." (PMID 35955723, 2022). "Furthermore, in an animal model for multiple sclerosis, they also showed that CD4+GranzB+CTLs are correlated with inflammation, demyelination, and disability." (PMID 34641948, 2021). "It ispossible that CD4+ T-cells in multiple sclerosis could exploitdisease-specific extravasation mechanisms, are more likely to extravasate ordisplay pro-inflammatory tendencies." (PMID 34761221, 2021). "CSF CD4+ T-cell countsin multiple sclerosis were significantly higher than those of NID controls in thisstudy (median in multiple sclerosis and NID controls 298.9 cells/ml and 81.6cells/ml, respectively; P = 1.4 ×10−6) and this is consistent with published data." (PMID 34761221, 2021). "Differential expression analysis of CD4+T-cells collected from the CSF highlighted genes involved in migration,activation, cholesterol biosynthesis and signalling, including those with knownrelevance to multiple sclerosis pathogenesis and treatment." (PMID 34761221, 2021). "In addition, we found that expansion of CD4 CTL correlates with worse prognosis in multiple sclerosis patients." (PMID 34073458, 2021).
multiple sclerosis (continued). "Gene expression differences specific to CSF CD4+ T-cells frompatients with multiple sclerosis could be relevant to pathogenesis." (PMID 34761221, 2021). "However, it is recognized that T lymphocytes play a central role in the pathogenesis of multiple sclerosis (MS), with CD4+ T cells predominating in acute MS lesions." (PMID 34001857, 2021). "While the contribution of autoreactive CD4+ T cells to the pathogenesis of Multiple Sclerosis (MS) is widely accepted, the advent of B cell-depleting monoclonal antibody (mAb) therapies has shed new light on the complex cellular mechanisms underlying MS pathogenesis." (PMID 33363512, 2020). "Upon knockout of Kdm6a in a classic mouse model of multiple sclerosis (CD4+ T cell–mediated experimental autoimmune encephalomyelitis), reduced inflammation and a reduction of spinal cord damage to neuronal axons were observed compared with wild-type counterparts." (PMID 33183347, 2020). "THOP1 gene suppression strongly affected the clinical performance of mice in experimental EAE: an animal model of multiple sclerosis, a chronic neuroinflammatory demyelinating disorder of the CNS with a marked neurodegenerative component initiated by CD4+ T cells." (PMID 31431000, 2019). "Another study reported that in multiple sclerosis patients, IL-11 could induce a differentiation of naive CD4+ Th cells into Th17 cells, as well as the expansion of Th17 memory cells." (PMID 30728748, 2019). "A trend towards decreased expression of EZH2 (p = 0.07) was observed in terminally differentiated effector CD4+ T cells from untreated multiple sclerosis patients compared to HC, and EZH2 expression was significantly upregulated in patients by the effect of natalizumab treatment (p = 0.03)." (PMID 30367633, 2018). "Of note, EZH2-positive cells both in CD4+ and CD8+ T cells may have pathogenic potential through the secretion of TNF-α, a pro-inflammatory cytokine involved in the pathogenesis of multiple sclerosis." (PMID 30367633, 2018). "Interestingly, in line with this, miR-326 and βarr-1 have been described to be key molecules in multiple sclerosis pathogenesis, being crucial for CD4+ T cell survival and differentiation." (PMID 28298929, 2017). "In the case of an animal model of multiple sclerosis (MS), experimental autoimmune encephalomyelitis (EAE), chemokine upregulation triggers the infiltration of central nervous system (CNS)-autoreactive CD4+ T cells (pathogenic CD4+ T cells) from the L5 dorsal vessels into the CNS." (PMID 29093711, 2017). "Of note CD4+ T cells from patients with multiple sclerosis had much higher Arrb1 expression and miR-326 expression was highly correlated with disease severity in patients with multiple sclerosis." (PMID 28298929, 2017). "Epstein-Barr virus (EBV) infection represents a major environmental risk factor for multiple sclerosis (MS), with evidence of selective expansion of Epstein-Barr Nuclear Antigen-1 (EBNA1)-specific CD4+ T cells that cross-recognize MS-associated myelin antigens in MS patients." (PMID 26849221, 2016). "Indeed, analysis the expression levels of Hrd1 detected a significant increase in Hrd1 mRNA expression levels CD4 T cells from the multiple sclerosis (MS) patients than that of healthy controls, suggesting a pathogenic role of Hrd1 elevation in human MS." (PMID 27417417, 2016). "Trafficking of myelin-reactive CD4+ T-cells across the brain endothelium, an essential step in the pathogenesis of multiple sclerosis (MS), is suggested to be an antigen-specific process, yet which cells provide this signal is unknown." (PMID 27336724, 2016). "IL-15 can enhance the cytotoxic potential of CD4+ T cells in multiple sclerosis." (PMID 26834537, 2015). "Notably, type I IFN, namely IFN-β, has previously been reported to inhibit spontaneous release of IL-22 from otherwise unstimulated CD4+ T cells obtained from multiple sclerosis patients." (PMID 26152778, 2015).